ARG1 (arginase 1)
Diseases named in the same sentence as ARG1 in open-access papers (continued):
Sharing a sentence is not in itself a finding about the gene and the disease.
non-small cell lung carcinoma (8 papers, 2015 to 2025). A group of at least three distinct histological types of lung cancer, including non-small cell squamous cell carcinoma, adenocarcinoma, and large cell carcinoma. "All non-small cell lung cancer cell lines secreted IL-8, and IL-8 was effective in triggering ARG1 release." (PMID 26819959, 2015). "For example, in patients with non-small cell lung cancer, TANs had reduced intracellular ARG1 and tumor-infiltrating lymphocytes showed reduced proliferation in response to CD3/TCR stimulation." (PMID 26819959, 2015). "Furthermore, tumor-infiltrating granulocytes in patients with non-small cell lung cancer or renal cell carcinoma have decreased ARG1 levels compared to their non-tumor-infiltrating counterparts, despite having increased ARG1 mRNA expression." (PMID 39211039, 2024). "Similarly, non-small cell lung cancer cells stimulated neutrophils through IL-8 to release ARG1, and in tumors TANs had reduced levels of ARG1." (PMID 26819959, 2015). "Recombinant human arginase 1 has previously been shown in vitro to suppress non-Hodgkin’s lymphoma cells, prostate cancer cells (LNCaP, DU-145, and PC-3), melanoma cells, laryngeal squamous cell carcinoma, leukemia cells, non-small cell lung cancer (NSCLC), and ovarian cancer cells." (PMID 36405587, 2022). "For instance, in human non-small cell lung cancer (NSCLC), Annexin A2 (ANXA2) signals through the TLR2/MYD88 axis in neutrophils, inducing ARG1 mRNA expression through amino acid depletion, which in turn inhibits T-cell viability." (PMID 40342932, 2025).
renal fibrosis (8 papers, 2020 to 2025). A final common manifestation of a wide variety of chronic kidney diseases characterized by glomerulosclerosis and tubulointerstitial fibrosis. "Inhibition of Ccr2 in AKI mice reduced the infiltration of Arg1+ macrophages and attenuated the progression of renal fibrosis." (PMID 40953007, 2025). "The M2-like phenotype (expression of markers like CD206 and arginase-1 (Arg-1)) at the later phases of repair is important for tissue repair, anti-inflammatory effects, and the prevention of renal fibrosis 8-10." (PMID 39494325, 2024). "Among these myeloid populations, the significance of Ly6c2+ and Arg1+ myeloid cells in renal fibrosis were observed." (PMID 38035106, 2023). "The fact that Arg1 protein was elevated in renal fibrosis suggests a possible contribution of Arg1 to the development and progression of renal fibrosis, possibly via its expression in infiltrating macrophages." (PMID 32956070, 2020). "Among these, only Mmp12 was highly expressed in the Ccl6+Ccr2+Arg1+ population, suggesting that these macrophages may contribute to the progression of renal fibrosis through tissue remodeling mechanisms." (PMID 40953007, 2025). "Intriguingly, Ly6C+ and Arg1+ myeloid cells also exhibited elevated levels of Fn1 and Vim in comparison to resident macrophages, suggesting a potential role of myeloid glycolysis in renal fibrosis initiation." (PMID 38035106, 2023). "We also confirmed that Ccl6+Ccr2+Arg1+ macrophages exhibit increased infiltration at day 7 post-AKI, with their infiltration level positively correlated with the degree of renal fibrosis." (PMID 40953007, 2025). "Collectively, our in vivo findings demonstrate that pharmacological inhibition of Ccr2 reduces macrophage infiltration and M2 marker (Arg1) expression in the kidney 7 days after AKI, as well as ameliorates renal fibrosis." (PMID 40953007, 2025). "Furthermore, the downregulation of Galectin-3 transcription has been associated with a reduction in inflammatory cell polarization and a decreased secretion of the profibrotic factors such as Arg-1, CD206, IL-10, and TGF-β, resulting in diminished renal fibrosis." (PMID 39407295, 2024).
Alzheimer disease (7 papers, 2014 to 2025). A progressive, neurodegenerative disease characterized by loss of function and death of nerve cells in several areas of the brain leading to loss of cognitive function such as memory and language. "Recent studies on murine models of Alzheimer’s disease have shown a link between ARG1 deficiency in microglial cells and amyloid formation." (PMID 37185755, 2023). "In recent decades, the abnormal expression of ARG-1 or ARG-2 has been reported to be increasingly linked to a variety of diseases, including cardiovascular disease, inflammatory bowel disease, Alzheimer’s disease, and cancer." (PMID 39861764, 2025). "Neuroinflammation induced by hypoxia activates M1 microglia and reduces M2 microglia by determining CD86 and Arginase-1 expression in Alzheimer’s disease." (PMID 37166426, 2023). "The APPswe/PS1ΔE9 mice results were consistent with the in vitro data, indicating a significant reduction in inflammatory cytokines and higher expression of M2-specific markers such as CD206 and Arg1 in C3G-treated Alzheimer’s disease model mice." (PMID 35670898, 2022). "Publications on the role of L-Arg metabolism in Alzheimer’s have demonstrated, for instance, that ARG1 mRNA level was increased in the cortex of the frontal lobe in patients with Alzheimer’s disease, without affecting ARG2 level." (PMID 37185755, 2023).
breast tumor (7 papers, 2018 to 2025). "On one hand, YHD inhibited the growth of 4T1 breast tumors via decreasing the number of MDSCs in the tumor microenvironment and through specific mechanisms associated with the downregulation of the expression of iNOS, ARG-1, IL-6, TGF-β, and p-STAT3." (PMID 30581487, 2018). "Recently, Su and colleagues demonstrated that breast-tumor-cell-derived GMCSF drives the accumulation of ARG1-expressing myeloid cells, well-known markers of inhibition of host antitumor immunity, and then dictates the acquisition of the immunosuppressive TME." (PMID 37686233, 2023). "Given the ability of monocytes to convert into macrophages and their engagement in the breast tumour microenvironment, we evaluated the expression of arginase-1 (Arg-1) as a marker of the M2 immunosuppressive phenotype." (PMID 36982588, 2023). "In addition, breast tumor cells stimulate arginase-1 expression in myeloid cells through GM-CSF secretion, thus creating an immunosuppressive microenvironment." (PMID 38177532, 2024). "Our results showed that The mechanisms of YHD inhibit 4T1 breast tumor growth may be related to downregulating the expression of iNOS and ARG-1, negatively regulating the Janus kinase/STAT3 (JAK/STAT3) pathway by repressing the expression of IL-6 and TGF-β." (PMID 30581487, 2018). "Artesunate, at varying concentrations, also suppressed the protein expression of HOXA5, WNT, β-catenin, Fizz1, and Arg-1, thereby modulating the WNT-β-catenin signaling pathway and ultimately curbing the proliferation of breast tumor cells." (PMID 40758729, 2025).
lung disease (7 papers, 2009 to 2025). "In chronic cystic fibrosis lung disease, neutrophilic inflammation and T-cell inhibition occur concomitantly, partly due to neutrophil-mediated release of the T-cell inhibitory enzyme Arg1." (PMID 37809107, 2023). "Predicting the effect of Pcc co-infection on long term Nb-induced lung disease is further complicated by recent data that suggest both Arginase-1 and RELMα can negatively regulate Th2-mediated pathology." (PMID 19951425, 2009). "For Arg1, we suggest that expression by fibroblasts might prove important for lung disease, since cell intrinsic arginase activity could promote fibrosis via proline to collagen and polyamine synthesis." (PMID 23637937, 2013). "Pulmonary disease progressed 12–16 wpi with lesions containing increased percentages of AFB, area of granulomatous pneumonia, iNOS+ macrophages, Arg1+ and double positive iNOS+/Arg1+ macrophages, and T cells." (PMID 35682679, 2022). "We then found increased numbers of ARG1+ cells by immunofluorescence of IPF lung explants acquired at the time of clinical transplantation compared with deceased donor lungs not known to have lung disease." (PMID 40875483, 2025).
lupus (7 papers, 2013 to 2025). "Arg-1 is commonly associated with anti-inflammatory responses, and in this study, its elevated expression in the kidneys of lupus mice may reflect a reduction in inflammation or improved immune regulation." (PMID 41161814, 2025). "Interestingly, the populations of MDSCs expressing immunoregulatory molecules including PD-L1, arginase-1, and IL-10 were significantly decreased in lupus patients." (PMID 33986739, 2021). "Interestingly, the mRNA levels of immunoregulatory molecules including PD-L1, arginase-1, and IL-10 were significantly decreased in lupus patients." (PMID 33986739, 2021). "Meanwhile, the expression of suppression-related molecules (arginase-1, IDO, PD-L1, and IL-10) in MDSCs was found to be profoundly decreased in lupus patients and mice." (PMID 37733169, 2024).
neuroblastoma (7 papers, 2015 to 2024). Neuroblastoma (NB) is the most common solid, extracranial childhood tumor. "In a more recent study using a mouse model of neuroblastoma, myeloid Arg1 expression promoted tumor growth." (PMID 36727849, 2023). "Conversely, in a commonly used neuroblastoma mouse model involving A/J mice injected with NXS2 neuroblastoma cells intravenously, M-MDSC displayed higher levels of Arg-1 and iNOS, and produced higher levels of TGF-β1 and ROS compared to PMN-MDSC." (PMID 38087370, 2023). "Arg-1 in neuroblastoma hindered myeloid activation and suppressed CD34+ bone marrow progenitor cell proliferation, suggesting that arginine deprivation contributes to MDSC induction in neuroblastoma." (PMID 38087370, 2023). "ARG1 overexpression increases ERK and AKT phosphorylation in neuroblastoma (NB), which promotes cell growth." (PMID 39051546, 2024).
periodontitis (7 papers, 2013 to 2025). An acute or chronic inflammatory process that affects the tissues that surround and support the teeth. "We observed that when tivantinib was administered to mice with ligature-induced periodontitis, Arg1+ cell numbers significantly decreased, indicating that inhibition of the HGF-Met signalling interaction in macrophages blocks their polarisation." (PMID 36193890, 2022). "The periodontitis group exhibited an elevated level of IL-6 and a lower level of ARG-1 compared to the healthy group, while in the cell injection group, the IL-6 level was significantly suppressed." (PMID 33195441, 2020). "Thus, it is conceivable that telocytes promote the overexpression of Arg1 in periodontitis which further leads to the M1/M2 state of macrophages." (PMID 36193890, 2022). "A moderate increase in Arg1 mRNA in the anti-BAFF-periodontitis group was also observed in the ligature-induced model, and the negative correlation between alveolar bone resorption severity and the level of Arg1 mRNA was to a statistically significant extent (r = − 0.8467, P < 0.001, n = 15)." (PMID 34481478, 2021).
acute myeloid leukemia (6 papers, 2019 to 2024). Acute myeloid leukemia (AML) is a group of neoplasms arising from precursor cells committed to the myeloid cell-line differentiation. "STAT3 inhibition also causes a reduction in ARG1 expression in patients with acute myeloid leukemia (AML), partially restoring T cell proliferation." (PMID 39337272, 2024).
amyloid (6 papers, 2015 to 2023). "At the same time, myeloid Arg1 deficiency during amyloidosis promoted gene signatures of lipid metabolism, myelination, and migration of myeloid cells." (PMID 34046031, 2021). "Second, we demonstrated that APP transgene mostly activated microglia/macrophages and myeloid Arg1 deficiency during amyloidosis promoted oligodendrocytes by analyzing cell-type-specific gene expression." (PMID 34046031, 2021). "First, our results showed the APP transgene activated Aβ plaque induced genes (PIGs) as the top changed signature and myeloid Arg1 deficiency during amyloidosis up-regulated it further." (PMID 34046031, 2021). "Collectively, the CPA data strongly suggest that APP transgene activates microglia/macrophages, and myeloid Arg1 deficiency during amyloidosis promotes oligodendrocytes, by which CNS cell types presumably drive the regulation of neurodegeneration." (PMID 34046031, 2021). "While there is considerable evidence supporting that myeloid Arg1 deficiency during amyloidosis exacerbates AD-typical neuropathology and behavioral impairments, the underlying mechanisms have yet to be fully clarified." (PMID 34046031, 2021). "Next, further investigation of individual glial signatures revealed that myeloid Arg1 deficiency during amyloidosis preferentially activated homeostatic microglia (HM) gene signature." (PMID 34046031, 2021). "Herein, we aim to determine how Arg1 deficiency driven by LysM restriction during amyloidosis affects fundamental neurodegenerative pathways at the transcriptome level." (PMID 34046031, 2021). "We previously reported Arg1 deficiency in myeloid biased cells using lysozyme M (LysM) promoter-driven deletion worsened amyloidosis-related neuropathology and behavioral impairment." (PMID 34046031, 2021). "These transcriptomic findings suggest a critical role for proper Arg1 function during normal and pathological challenges associated with amyloidosis." (PMID 34046031, 2021). "Collectively, these transcriptomic findings suggest myeloid Arg1 deficiency activates gene signatures of lipid metabolism and myelination and promotes myeloid cell migration in the mouse brain of amyloidosis." (PMID 34046031, 2021). "Future studies should increase replication with a larger sample size and compare these targeted transcriptome results with larger transcriptome dataset to ensure the effects of myeloid Arg1 deficiency during amyloidosis." (PMID 34046031, 2021). "Therefore, we sought to repress Arg1 in myeloid cells to assess the impact of Arg1 deficiency in the mouse brain during the amyloidosis challenge." (PMID 34046031, 2021). "Our study remains unclear if/how Arg1 deficient microglia regulate myelination during amyloidosis based on transcriptomic evidence." (PMID 34046031, 2021). "Therefore, our data suggest that reduced Arg1 in myeloid cells promotes transcript signatures associated with demyelination or delayed remyelination during the amyloid challenge." (PMID 34046031, 2021). "Since the myeloid marker gene Lyz2 targets both macrophages and microglia, the observed consequence of exacerbated amyloidosis from the current study were possibly attributed to the deficiency of Arg1 in both brain resident microglia and CNS infiltrated macrophages." (PMID 33519806, 2020). "Deficiency of Arg1 in brain myeloid cells preferentially promotes a transcriptomic signature that is more homeostatic and less phagocytic, possibly inhibiting their crucial transition from a homeostatic to a disease-associated state during amyloidosis, leading to more Aβ deposition." (PMID 34046031, 2021). "However, it remains unclear how Arg1 deficiency in these cells impacts the whole brain to promote amyloidosis." (PMID 34046031, 2021). "Other studies have found that ARG1+ microglia cells phagocytized beta-amyloid components and contributed to amyloid plaque reduction." (PMID 37185755, 2023).
amyloid (continued). "Considering the beneficial role of overexpressing Arg1 in the tau transgenic mouse model, a future study on overexpressing Arg1 in a mouse model of amyloidosis should be investigated." (PMID 34046031, 2021). "By laying a foundation for the role of Arg1 in phagocytic myeloid cells during amyloidosis, we provided a new therapeutic target for manipulating arginine metabolism through arginase 1 to benefit human AD." (PMID 34046031, 2021). "Previously we sought to investigate the impact of reduced myeloid Arg1 in the APP Tg2576 mouse model of amyloidosis." (PMID 34046031, 2021). "Conversely, another study using the CVN-AD mouse model (Nos2 null) showed that sustained elevated extracellular Arg1 level stimulated amyloidosis and promoted hippocampal neuronal death." (PMID 34046031, 2021). "In the current study, our data suggest that insufficient myeloid Arg1 expression during amyloidosis activates transcriptomic pathways in myelination, lipid metabolism, and glial gene signatures that are primarily homeostatic and non-phagocytic." (PMID 34046031, 2021). "The findings were in line with our previous report that myeloid Arg1 insufficiency promoted amyloidosis, confirming that the magnitude of PIGs positively correlated to the load of Aβ deposition." (PMID 34046031, 2021). "We performed bulk RNA transcriptome analysis to determine the transcriptional pathway changes following myeloid Arg1 haploinsufficiency during amyloidosis." (PMID 34046031, 2021). "Overall, our findings imply that the haploinsufficiency of Arg1 in myeloid cells during amyloidosis exacerbates AD-like neuropathology, neuroinflammation, and behavioral deficits." (PMID 33519806, 2020). "In summary, mice with amyloidosis display impaired behaviors activities, anxiety, and memory, while Arg1 insufficiency exacerbated these effects." (PMID 33519806, 2020). "Collectively, these data strongly suggest that Arg1 insufficiency during amyloidosis promotes diffuse Aβ 42 deposition." (PMID 33519806, 2020). "In the present study, we found that the haploinsufficiency of Arg1 in myeloid cells in a mouse model of amyloidosis increased Aβ deposition, activated microglia, and impaired behavioral performance." (PMID 33519806, 2020). "In the current study, by using conditional LysMcre deletion in APP Tg2576 transgenic mice, we are the first to measure the specific effect of reducing Arg1 in myeloid cells in responding to amyloidosis." (PMID 33519806, 2020). "Collectively, these data support the overall concept that Arg1 insufficiency in myeloid cells exacerbates amyloidosis induced neuropathology possibly by activating microglia and impairing phagocytosis." (PMID 33519806, 2020). "To assess how Arg1 insufficiency in myeloid cells impacted amyloidosis, we crossbred LoxP Arg1 (Arg1fl/fl) mice with transgenic APP Tg2576 mice (APP+/−) to generate APP(+/−)/Arg1(fl/−) and APP(−/−)/Arg1(fl/−) (non-transgenic, nTg) mice." (PMID 33519806, 2020). "Next we measured microglial markers in various regions of the brain by immunohistochemistry during amyloidosis and Arg1 insufficiency." (PMID 33519806, 2020). "Another group reported Arg1 positive microglia were responsible for reducing Aβ plague deposition during sustained neuroinflammation in an amyloidosis mouse model." (PMID 33519806, 2020). "We performed immunohistochemical analysis, mouse behavioral assessments, and biochemical analysis in mice of amyloidosis and Arg1 haploinsufficiency." (PMID 33519806, 2020). "Furthermore, our pathway analyses showed that myeloid Arg1 haploinsufficiency during amyloidosis also up-regulated the lipid metabolism gene set." (PMID 34046031, 2021). "Despite increased microglia activation measured by IBA1 and CD68, these data strongly suggest that several components of the Ragulator-Rag complex are up-regulated during amyloidosis and reduced with Arg1 insufficiency, indicating a potential deficit in microglial digestion machinery." (PMID 33519806, 2020).